CD14 (CD14 molecule)
Diseases named in the same sentence as CD14 in open-access papers (continued):
Sharing a sentence is not in itself a finding about the gene and the disease.
viral infection (continued). "The accumulation of CD14+HLA-DRhighCD206+ in pathological liver is directly linked to gut intestinal microbiota but not viral infection." (PMID 38413535, 2024). "As an indicator of systemic innate immune activation following SIV infection, we determined the induction of CD169 expression on CD14+ classical monocytes, a response that has been shown to be upregulated by type 1 interferon and other TLRs triggered by viral infection." (PMID 38593120, 2024). "Functional enrichment analysis of the signature genes highly expressed in the cluster of CD14+STAT2high revealed that pathways related to virus infection and type I interferon were significantly enriched, suggesting a key role of the CD14+STAT2high cluster in type I interferon responses." (PMID 39339845, 2024). "HLA-DRlow CD14+ monocytes, a regulatory myeloid cell subtype that trended toward expansion in SDp, may also promote Treg expansion, as shown in other viral infections." (PMID 36961888, 2023). "Our bulk transcriptomic analysis of CD14+ cells during viral infection also indicates that the enrichment in circulating CD14+CD16+ coincided with the upregulation of both inflammatory and anti-inflammatory gene sets in monocytes, which could fit this model." (PMID 37920474, 2023). "In addition to their relevance in the mechanism of action of R848, our data argue for an involvement of γδ T and CD14+CD16+ cell-mediated responses during natural viral infections, when TLR8 ligands are produced." (PMID 29312324, 2017). "Secondary infection and DHF were associated with higher viral burden in PBMC populations, especially CD14+ monocytes, suggesting that viral infection of these cells may be involved in disease pathogenesis." (PMID 23284680, 2012). "We used molecular and cellular analyses to determine if WMS had significant effects on innate immune responses to viral infection and observed a significant increase in both CD14 expression and LPS responsiveness during viral infection and prior to secondary bacterial challenge." (PMID 22435642, 2012). "Thus, increased expression of TLR4 and CD14 in PBMCs cannot be explained by a simple increase in monocyte frequency following viral infection." (PMID 22435642, 2012). "In response to inflammation and viral infection, there is an expansion of more mature CD14+CD16+ and CD14loCD16+ monocyte populations first with acute infection and again with the development of AIDS, when these cells can represent up to 40% of the total circulating monocyte population." (PMID 21494695, 2011). "In order to test whether this variability contributes the large variation in gene induction with virus infection, we sorted cells into high and low CD14 subpopulations prior to infection with virus." (PMID 21347441, 2011). "LY6E downregulates CD14, a key molecule in the TLR4/CD14/NF-κB pathway, inducing a negative feedback loop for innate immune activation and providing a new pathway for viral infection." (PMID 38169284, 2024). "The upregulation of IFN-related genes in B, CD14+, CD4+, and CD8+ cells is indicating that the host is detecting the presence of the viral infection and consequently activating the IFN response." (PMID 37920474, 2023). "The interferon signaling pathway that is essential for increased cellular resistance to viral infection was found activated at 5 dpv in CD4+, CD8+, and CD14+ cells of both species." (PMID 33785572, 2021). "The mechanisms underlying the differential influence of CD14+ versus CD16+ monocytes and decoupling between the IFN-response and protective response remain unknown, though mounting evidence suggests dysfunctional myeloid cells in patients with severe viral infection." (PMID 33765435, 2021). "RIG-I-like receptors (RLRs): RIG-1, LGP2, and MDA-5 that sense viral infection were found to be predominant in CD4+, CD8+, and CD14+ cell subsets at 5 dpv in goats and in CD4+ and CD14+ cell subsets of sheep." (PMID 33785572, 2021).
viral infection (continued). "In the absence of enhancing serum, the ZIKV infection was barely detectable at an MOI of 0.2 or 2, whereas higher levels of virus infection were observed at an MOI of 20 in PBMCs and CD14+ monocytes." (PMID 30044839, 2018). "We show that airway epithelium-derived CD14 did not affect RSV viral infection and that CD14 on immune cells impaired the immune response against RSV." (PMID 35429403, 2022). "This appears to be part of virus infection-induced alterations to support virus replication as shown here through a reduced IFN response and an increase in number of extracellular virus particles after antibody-mediated blockage of CD14." (PMID 35203475, 2022). "Because monocytes and macrophages expressing CD14 are more susceptible to HIV infection, the host immune response to viral infection rather than the drug toxicity is of particular importance in this shift of macrophages toward M1 phenotype." (PMID 35246167, 2022). "These monocyte subsets (CD14++CD16+ and CD14+CD16++) have been also reported in HCV infection demonstrating that CD16+ monocytes may play important role in viral diseases." (PMID 25835530, 2015). "Cytokine production after virus infection of CD19+, CD14+, CD56+, CD3+ monocultures and PBMCs." (PMID 19125202, 2009). "While our case demonstrated the emergence of a subpopulation of monocytes expressing partly upregulated CD16 and partly weaker CD14 that were concurrent with the peak of infection, the presence of promonocytes could not be explained by a viral infection and was concerning for a second etiology." (PMID 38921181, 2024). "A statistically significant increase in PAD2 expression was observed after 48 h RV1B MOI 5 infection, in the CD14− CD16++ subset, confirming that HRV viral infection is also able to increase PAD2 levels in non-epithelial cells." (PMID 32117246, 2020). "In contrast, the expression of CD14 and PDL2 was not significantly altered in response to viral infection." (PMID 25775126, 2015). "The proportion of CD14+ monocytes increased significantly in patients with non-severe (ES = 1.12, FDR = 1.30e-21) and severe (ES = 0.9, FDR = 6.56e-10) viral infection compared to HCs, but were not different between patients with non-severe or severe viral infection." (PMID 33765435, 2021).
periodontitis (49 papers, 2012 to 2025). An acute or chronic inflammatory process that affects the tissues that surround and support the teeth. "While evidence supports the potential role of CD14 -159 gene polymorphism in the development of periodontitis, few studies have refuted the involvement of this genetic variation in periodontitis incidence." (PMID 40673119, 2025). "CD14 has been considered as a causative gene for periodontitis, and is implicated in periodontal tissue remodeling and degradation." (PMID 38629742, 2024). "Regarding periodontitis, two polymorphisms of the CD14 encoding gene were studied, replacement of cytosine (C) with thymine (T) at position −159, described as −159 (C→T), and −1359 (G→T)." (PMID 35454140, 2022). "So far, a number of studies have evaluated the association between PRRs, SNPs, and periodontitis, including CD14, TLR2, TLR4, and MBL2." (PMID 32831974, 2020). "The present study supports the notion that a T/T genotype at the -159 position of the CD14 gene is associated with chronic periodontitis." (PMID 23046822, 2012). "Previous studies have shown an association of the CD14-159 TT genotype with chronic periodontitis, myocardial infarction and pulmonary tuberculosis." (PMID 23046822, 2012). "CD14 is a protein involved in the detection of bacterial lipopolysaccharide (LPS) and has also been associated with periodontitis." (PMID 23046822, 2012). "Currently, CD14 gene polymorphisms are considered as potential diagnostic markers for periodontitis." (PMID 23046822, 2012). "Our data showed that decitabine inhibited bone loss and osteoclast differentiation experimental periodontitis, and suppressed osteoclast CD14+ human monocytes; and conversely, that it increased bone mineralization in osteoblastic cell line MC3T3-E1 in a concentration-dependent manner." (PMID 33671221, 2021). "Considering SNP rs2569190 in the CD14 gene, an association of this SNP with periodontitis could be shown in highly selected case-control studies." (PMID 34305452, 2021). "CD14 variant was found to be associated with the severity of periodontitis." (PMID 31281226, 2019). "In this study, we hypothesized that the expression of TLR4 or TLR4-associated molecules such as CD14, MD-2 and MyD88 are regulated by periodontitis and T2DM." (PMID 26581717, 2015). "Within the limitations of the study, the present findings suggest that DEFB1 and CD14 gene polymorphisms are significantly associated with chronic periodontitis and could possibly be potential markers for assessment of risk for periodontal disease." (PMID 23046822, 2012). "Our data reported herein demonstrate that HFD-induced metabolic disturbances were associated with the occurrence of periodontitis, and that chronic estrogen administration, as well as the deletion of CD14, strongly prevents the HFD-induced defects of periodontal tissue in mice." (PMID 23133617, 2012). "The current findings on an increased detection frequency of T/T genotype in parallel with an increased serum level of CD14 protein is consistent with other studies on genetic polymorphisms of CD14 gene where the T/T genotype is also shown to be more frequent in severe periodontitis." (PMID 23046822, 2012). "Studies have explored histocompatibility antigen polymorphisms, IgG class antibody receptor polymorphisms, CD14 molecule polymorphisms, toll-like receptor polymorphisms, vitamin D receptor polymorphisms, and other cellular receptor polymorphisms in relation to chronic and aggressive periodontitis." (PMID 37927745, 2023). "However, previous studies suggested that a bacteremia that is caused by periodontitis might induce cytokines to change the immune cell function (e.g. developing CD14+ and CD16+ monocytes)." (PMID 25299619, 2014).
periodontitis (continued). "Considering the association of CD14 genetic polymorphisms with the severity of chronic periodontitis, the present study investigated for the first time the potential association of both hBD and CD14 polymorphisms and their serum levels with chronic periodontitis in Chinese subjects." (PMID 23046822, 2012). "Patients with chronic periodontitis exhibit a notable increase in CD14 + CD16 + monocytes in their peripheral blood, indicating a systemic shift in immune cell distribution." (PMID 39014403, 2024). "As reported in a meta‐analysis, CD14 ‐159C/T has been suggested to be involved in the development of periodontitis, which was in accordance with our present results." (PMID 38629742, 2024). "Periodontitis saliva significantly reduced the percentages of CD14+, CD68+, and CD36+ cells versus healthy saliva, indicating a nudge of the monocytes and M0-type macrophages toward an inflammatory status but away from the M2 phenotype." (PMID 36207325, 2022). "CD14 biomarker expressed on PMNs acts as a receptor for the LPS of gram-negative bacteria and studies reported higher expression levels of CD14 on oPMNs of patients with periodontitis compared to healthy individuals." (PMID 36552874, 2022). "The difference in CD14+ distribution was much more substantial in periodontitis patients’ samples compared to healthy controls (p < 0.001)." (PMID 36261500, 2022). "Lipopolysaccharide induced the expression of CCL5 in CD14 + sorted cells from gingival crevicular fluid of periodontitis patients." (PMID 36414950, 2022). "Moreover, soluble monocyte differentiation antigen (CD14) has been described as a crucial factor influencing the susceptibility of human periodontal ligament stem cells to different pathogens and thus may contribute to the progression of periodontitis." (PMID 34064456, 2021). "And indeed, in a variety of case-control studies as well as in meta-analyses, their impact on periodontitis as well as CV diseases was assessed (CD14, NF-κΒ, TLR2, and TLR4)." (PMID 34305452, 2021). "In context of oral inflammation (periodontitis), pro-inflammatory CD14+ monocytes were clearly increased in diabetic individuals." (PMID 34858391, 2021). "MMP-12 expression found elevated in patients with chronic periodontitis with identification of CD68+ CD14+ CD64+ cells." (PMID 33892690, 2021). "Possible associations between SNPs in CD14 (rs2569190), NF-κB (rs28362491), TLR2 (rs5743708), and TLR4 (rs4986790) and the occurrence of severe periodontitis were investigated in the cohort of CV patients." (PMID 34305452, 2021). "The GCF samples obtained from periodontitis patients were used to treat CD14+ monocytes obtained from peripheral blood of healthy donors." (PMID 34203667, 2021). "A significantly higher proportion of intermediate (CD14+CD16+) monocytes was observed in periodontitis-affected tissues compared to healthy tissues." (PMID 32210958, 2020). "Several case-control studies also found increased serum concentration of CD14 among the patients with periodontitis." (PMID 30760334, 2019). "Taken together, it seems likely that the rapid cleavage of CD14 and consequent failure for efficient AC clearance will promote defective control of inflammation in periodontitis." (PMID 28252646, 2017). "These support the notion that failure to uptake apoptotic NØ following gingipain cleavage of specific receptors, for example, CD14, will drive necrosis resulting in connective tissue matrix destruction in periodontitis." (PMID 28252646, 2017). "Another study shows that the levels of sCD14 in whole saliva is higher in periodontitis patients than in healthy controls and that salivary CD14 level exhibit a significant positive correlation with clinical measurements of periodontitis." (PMID 27504628, 2016). "The genotype frequencies of CD14 in periodontitis patients were 10% for C/C, 43% for T/T and 47% for C/T." (PMID 23046822, 2012).
periodontitis (continued). "This study investigates the single nucleotide polymorphic (SNP) region, -1654(V38I), of the human beta-defensin-1 (hBD-1) gene as well as the -159 region of the CD14 gene in subjects with chronic periodontitis." (PMID 23046822, 2012). "Even within the periodontitis group, subjects with the T/T genotype exhibited higher levels of CD14 than subjects with C/C or C/T genotypes." (PMID 23046822, 2012). "It is interesting to note the serum levels of CD14 in the periodontitis group was significantly higher than the levels in the controls." (PMID 23046822, 2012). "The results from this study established the detection frequency of CD14 T/T genotype in periodontitis patients (43%) to be significantly greater than periodontally healthy controls (26%)." (PMID 23046822, 2012). "Results of our study discovered that the most significant crosstalk genes between periodontitis and MS were FAM46C, SLC7A7, LY96, CFI, DDIT4L, CD14, and IGJ, which may be associated with response to molecules of bacterial origin." (PMID 38218802, 2024). "Soluble CD14 level in saliva of patient's chronic periodontitis is proved to rise." (PMID 39113346, 2024). "Based on the data available, we assessed in our study the impact of SNPs in TLR2 (rs5743708), TLR4 (rs4986790), CD14 (rs2569190), and NF-κΒ (rs28362491), on severe periodontitis as well as on the incidence of new CV events within a three year follow-up in a cohort of CV patients." (PMID 34305452, 2021). "The study further aimed to assess if GCF of periodontitis patients could convert CD14+ monocytes into macrophages of destructive phenotype in an in vitro setting." (PMID 34203667, 2021). "Thus, the aim of this study was to evaluate the influence of the polymorphisms in TLR4 (rs4986790 and rs4986791), CD14 (rs2569190), RANKL (TNFSF11, rs2277438), and OPG (TNFSF11B, rs3102735) in the development of periodontitis." (PMID 31281226, 2019). "Thus, the aim of this study was to evaluate the influence of the TLR4 A896G (rs4986790), TLR4 C1196T (rs4986791), CD14 C-260T (rs2569190), RANKL (TNFSF11, rs2277438), and OPG (TNFSF11B C163T, rs3102735) polymorphisms in periodontitis." (PMID 31281226, 2019). "Nevertheless, it remains unclear how CD14 expression is further downregulated by T2DM and more studies are necessary to elucidate the mechanisms by which periodontal CD14 expression is downregulated by periodontitis and T2DM." (PMID 26581717, 2015). "The finding that CD14 was downregulated in patients with periodontitis may also reveal a negative feedback mechanism by which periodontal tissue of patients with periodontitis prevent further damage from repeated attacks by bacteria-derived LPS." (PMID 26581717, 2015). "Therefore, it is likely that TGFβ1 plays a role in the downregulation of periodontal CD14 expression in patients with periodontitis." (PMID 26581717, 2015). "This study purely investigated the association between periodontitis and one polymorphic site on both DEFB1 and CD14 gene, with the purpose of expanding knowledge for the future development in diagnostic markers or therapeutic interventions to combat this disease." (PMID 23046822, 2012). "The present study aimed to quantify the cytokine profile of GCF samples obtained from patients with periodontitis and sought to examine whether GCF of periodontitis patients could convert CD14+ monocytes into macrophages of destructive phenotype in an in vitro setting." (PMID 34203667, 2021). "As TLR4 and CD14 were previously associated with LPS hyporesponsiveness and RANKL and OPG to the regulation of bone mass, we hypothesized that the polymorphisms in the genes that codified these proteins could influence the pathogenesis of periodontitis." (PMID 31281226, 2019).